IL6 (interleukin 6)
Diseases named in the same sentence as IL6 in open-access papers (continued):
Sharing a sentence is not in itself a finding about the gene and the disease.
pterygium (continued). "IL-6 is a proinflammatory cytokine which is upregulated in pterygium by UV light exposure and might be part of the pathological pathway leading to the formation of the lesion." (PMID 22724003, 2012). "The upregulation of IL-6 after treatment with doxycycline may be also part of the survival program of the pterygium cells faced by the harsh conditions created by the antibiotic." (PMID 22724003, 2012). "Furthermore, results of the association analysis show a linear relationship between IL-6 and VEGF, strengthening the hypothesis that IL-6 signalling stimulates VEGF secretion in pterygium." (PMID 31780873, 2019). "A recent study has explored several potential targets to reduce pterygium recurrence, including NLRP3, TGF-β1, VEGF, IL-6, and IL-8." (PMID 39682531, 2024). "Other cytokines (IL-6, IL-8, IL-1β, and TGF-β1) were detected at similar levels in both primary and recurrent pterygium (p = 0.2986)." (PMID 39682531, 2024). "Tear IL-6, IL-18, and VEGF concentrations of the primary pterygium patients were very similar to those of the recurrent pterygium patients." (PMID 33531557, 2021). "In our study, IL-6, IL-18, and VEGF concentrations in pterygium patients and HCs with DE were significantly higher at 4.16–8.86, 14.85–25.93, and 3.41–8.98 times higher, respectively, than those of the other groups without DE." (PMID 33531557, 2021). "Because of the uncertainty of the pterygium pathogenesis, a review analyzed several cytokines involved in pterygium fibrovascular growth, especially vascular endothelial growth factor (VEGF), interleukin (IL)-6, and IL-1813,14." (PMID 33531557, 2021). "Our data show that, in the affected eyes, the subsequent decrease of the IL-6, IL-8, and VEGF following the 2W-PO elevation corresponds well with the recovery status of the pterygium patients." (PMID 31780873, 2019). "The potential application of IL-6, IL-8, and VEGF concentrations to predict the outcome of pterygium surgery was based on their evolution over time." (PMID 31780873, 2019). "We established a role for IL-6, IL-8, and VEGF in pterygium pathology, manifesting as a clear change and an eventual decrease in tear film levels one year after the surgery." (PMID 31780873, 2019). "The balanced IL-6, IL-8, and VEGF tear film secretions in normal subjects are thought to become elevated during pterygium initiation, which is triggered by UVB radiation." (PMID 31780873, 2019). "Next, the effect of MMC injection on the expression of inflammatory factors including TGF-β1, VEGF, IL-6, IL-8, and TNF-α that have been reported to be highly expressed in pterygium tissues were also evaluated." (PMID 31827916, 2019). "One study found that IL-6 levels increase in inflammatory events regardless of the characteristics of pterygium." (PMID 39682531, 2024). "Furthermore, tear films of patients surgically treated for pterygium show a clear change and decrease in VEGF and IL-6/8 levels one year after surgery, emphasizing their role in pterygium pathology." (PMID 34206333, 2021). "In this way, increases in the interleukins IL-1, IL-6, and IL-8 and the tumor necrosis factor TNF-α have been described as contributing to the recruitment of other inflammatory mediators and metalloproteases involved in pterygium pathogenesis." (PMID 34945227, 2021). "In addition, we examined potential correlations between (I) the preoperative (pre-OP) IL-6, IL-8, and VEGF levels; (II) the overall vascularized area of the cornea (%); and (III) the area of the cornea covered by pterygium (%)." (PMID 31780873, 2019). "Given the background on IL-6, IL-8, and VEGF, we aimed to quantify their concentrations in the tear film over time and to determine whether these levels could be used to predict pterygium recovery and/or recurrence." (PMID 31780873, 2019).
pterygium (continued). "The geometric mean of the IL-6 concentration in the HCs with DE was 8.86 times higher (95% CI 2.49–31.50) than that of the HCs without DE (p < 0.001) and 4.60 times higher (95% CI 2.11–10.02) than the pterygium groups without DE (p = 0.001)." (PMID 33531557, 2021). "The relationship between (I) the pre-OP cytokine production (IL-6, IL-8, and VEGF), (II) the vascularization index, and (III) the area which was determined in patients with PPt (Supplementary ) and RPt (Supplementary ) and all pterygium patients as a group (n eyes = 21, PPt+RPt)." (PMID 31780873, 2019). "More importantly, our findings reveal that MMC reduces the recurrence rate of pterygium by suppressing angiogenesis and fibroblast proliferation via inhibiting NLRP3/Caspase-1 pathway activation and the expression of inflammatory factors such as TGF-β1, VEGF, IL-6." (PMID 31827916, 2019). "We also evaluated the association between fleshiness and pterygium extension and compared the levels of cytokines, including IL-6, IL-18 and VEGF, in the tears of primary pterygium patients, recurrent pterygium patients and participants without ocular disease." (PMID 33531557, 2021). "Tear IL-6, IL-18, and tear VEGF were significantly higher in participants with DE, regardless of pterygium status." (PMID 33531557, 2021). "Nonetheless, the lack of relationship between IL-6/VEGF and the vascularization index indicates that IL-6 and VEGF are not decisive factors in pterygium pathology." (PMID 31780873, 2019). "Tretinoin, an anti-inflammatory/angiogenesis agent, was testified to reduce IL-6, IL-8, and VEGF production in pterygium in study model, but has not been applied clinically." (PMID 31341891, 2019). "A number of studies have relatively frequently reported the role of other ECM components in pterygium not related to fibroblasts or TGF-β, such as MMPs, different growth factors (PDGF, bFGF, HB-EGFM, and VEGF), or inflammatory mediators, such as IL-6 and IL-8." (PMID 34945227, 2021).
radiation pneumonitis (17 papers, 2008 to 2025). Inflammation of the lung due to harmful effects of ionizing or non-ionizing radiation. "IL-6 has also been implicated in the pathogenesis of radiation pneumonia and is synthesized by type II pneumocytes, alveolar macrophages, T lymphocytes, and lung fibroblasts." (PMID 20374625, 2010). "The study summarized as high pretreatment plasma levels of IL-6 predisposed patients to the risk of radiation pneumonitis and therefore pretreatment IL-6 level may serve as a predictor for radiation pneumonitis." (PMID 28512460, 2017). "In humans, some clinical series have shown changes in the plasma concentrations of TGF-β1 and IL-6 during radiotherapy suggesting that these variations could identify patients at risk of radiation pneumonitis." (PMID 19320990, 2009). "Radiation‐induced ALKBH5 mediated m6A demethylation of IL‐6 mRNA and reduced IL‐6 production to alleviate radiation pneumonitis." (PMID 36792369, 2023). "A similar study was conducted to observe the changes of IL-6 during radiation pneumonitis, along with combined covariations of IL-6 and IL-10." (PMID 28512460, 2017). "It was noticeable that except TNF-α, there was a consistently elevated level of IL-1α and IL-6 prior to and throughout treatment in patients having radiation pneumonitis." (PMID 28512460, 2017). "Patients with radiation pneumonitis demonstrated higher circulating levels of IL-6 during and immediately after thoracic radiotherapy." (PMID 28512460, 2017). "Clinical as well as experimental findings have suggested the involvement of IL-6 as a pro-inflammatory cytokine in radiation pneumonia." (PMID 20374625, 2010). "IL-1β and IL-6 are the major cytokines in radiation pneumonitis." (PMID 39575431, 2024). "The circulating IL-6 concentration is a predictor of radiation pneumonitis." (PMID 39619013, 2024). "However, the mechanism for IL-6 involvement in radiation pneumonitis warrants further investigation." (PMID 28512460, 2017). "Interleukin 6 (IL6) and connective tissue growth factor (CTGF) were selected, as both were identified by gene expression analysis of breast tissue, and are implicated in the pathogenesis of radiation fibrosis." (PMID 24885397, 2014). "Two candidate cytokines were selected as possible biomarkers of radiation fibrosis, IL6 and CTGF." (PMID 24885397, 2014). "Indeed, up-regulation of IL-6 production has been observed in human and animals with radiation pneumonia." (PMID 20374625, 2010). "Additionally, the tight correlation (R2 = 0.97) between tissue and serum levels suggests that blood IL-6 could be a good predictor for radiation pneumonitis." (PMID 19187543, 2009). "Barthelemy-Brichant and coworkers found no relation between IL-6 and radiation pneumonitis and a multicytokine analysis of plasma of patients showed that only low pre-treatment levels of IL-8 were predictive of radiation pneumonitis." (PMID 22216271, 2011). "The aim of the present study was to investigate the prognostic value of TNF-α, IL-1β, IL-6 and TGF-β1 plasma levels to predict radiation pneumonitis and to evaluate the impact of tumour-derived cytokine production on circulating plasma levels in patients irradiated for NSCLC." (PMID 18682839, 2008). "Radiation pneumonitis develops within hours or days of lung IR and is accompanied by increased capillary permeability, leukocyte infiltration, and release of cytokines, such as transforming growth factor β (TGF-β), interleukin 6 (IL-6), tumor necrosis factor alpha, and interleukin-1 beta (IL-1β)." (PMID 32811815, 2020). "Furthermore, persistently elevated IL1a (interleukin 1 alpha) and IL6 (interleukin 6), ICAM 1 (intercellular adhesion molecule 1), SP-A (surfactant protein A) and SP-D (surfactant protein D) serum levels are predictive for the development of radiation pneumonitis." (PMID 33521012, 2020).
Respiratory distress (17 papers, 2017 to 2026). Respiratory distress is objectively observable as the physical or emotional consequences from the experience of dyspnea. "Importantly, low 25OHD levels at hospital admission were associated with increased IL-6 levels and predicted both the severity of respiratory distress and mortality during the course of hospitalization, independently of other comorbidities." (PMID 34126960, 2021). "The levels of soluble ICAM in serum, a marker of systemic inflammatory response, endothelial cell activation and acute respiratory distress, were comparable between WT and IL-6 KO mice." (PMID 33193346, 2020). "In model 1, respiratory distress (p = 0.9999) and IL-6 (p = 0.0130) are the only variables that affect HCPS outcome." (PMID 28708900, 2017). "It was demonstrated that IL-6 was elevated in the serum of severely infected patients experiencing respiratory distress and admitted to the ICU, hence making IL-6 an important marker to evaluate disease severity and early stratify patients at risk to progress into complications." (PMID 35062368, 2022). "Furthermore, higher plasma levels of IL-6, IL-1β, IL-8, CCL2, (among other markers such as TNF-α) and IL-6 were also associated with post-TBI mortality, whereas higher levels of IL-6 and IL-8 were associated with respiratory distress in TBI patients." (PMID 37415924, 2023). "The PB group showed higher rates of respiratory distress, longer hospital stays, longer fever durations, and elevated levels of neutrophil percentage, CRP, PCT, IL-6, LDH, SF, D-dimer, and ALT." (PMID 42220983, 2026). "In the later phase, IL-6 levels are similar in severe and moderate illness, but NETosis-complement-coagulation leads to immunothrombosis, compounded by reduced clearance of the NETs (due to decreased levels of DNASE1), ultimately leading to acute respiratory distress in the severe cases." (PMID 34775962, 2021). "The sensitivity to IL-6 concentration before AST-monitored organ damage suggests anti-IL-6 therapeutics could be an effective tool for management in the early and rapidly progressive stages of respiratory distress for αEp9-positive patients (31, 37, –, 41)." (PMID 33910993, 2021).
septic arthritis (17 papers, 2013 to 2025). "Here we show that in the mouse model for hematogenous septic arthritis, the Δnuc1 mutant is much less pathogenic and the severity of clinical septic arthritis is markedly reduced, including decreased weight loss, lower kidney bacterial load, reduced bone erosion, and much less IL-6 production." (PMID 40210969, 2025). "IL-6 levels have been positively correlated with the severity of septic arthritis and weight loss." (PMID 39204252, 2024). "TNF-α, IL-1β, and IL-6 have been indicated as being the main cytokines that lead to severe inflammation that precedes cartilage and bone destruction in septic arthritis." (PMID 40005560, 2025). "This phenomenon appears to be associated with an elevated bacterial burden in the blood and kidneys, along with reduced systemic levels of TNF-α and IL-6, resulting in higher mortality in mice with hematogenous S. aureus septic arthritis." (PMID 40067374, 2025). "To sensitively, specifically and quickly diagnose septic arthritis, several synovial fluid host-specific biomarkers, including interleukin-6, adenosine deaminase, alpha-defensin, leukocyte esterase, and calprotectin, were evaluated." (PMID 34656157, 2021). "Sera collected at the end of the first septic arthritis experiment was analyzed for levels of IL-6, TNF-α, IFN-γ, MCP-1 and RANKL by ELISA." (PMID 32616791, 2020). "Synovial concentrations of the proinflammatory markers TNFα, IL-1β, and IL-6 are elevated in the course of disease, in which TNFα was a better indicator to discriminate bacterial arthritis from other inflammatory arthritis." (PMID 27688601, 2016). "The study aimed to evaluate the diagnostic performance of routinely used and novel biomarkers, including serum C-reactive protein (CRP), synovial white blood cells (WBC), pentraxin-3 (PTX3), interleukin-6 (IL-6), and presepsin, in distinguishing septic from non-septic arthritis." (PMID 40807041, 2025). "Ghosh and colleagues described that neutralization of TGF-β and IL-6 ameliorated septic arthritis by modulating tissue-resident macrophages; RANKL/OPG interaction (preventing bone loss); and enhancing the antioxidant activity of superoxide dismutase and catalase." (PMID 40005560, 2025). "First, the number of patients diagnosed with septic arthritis was relatively small, which may have limited the statistical power, particularly for evaluating individual novel biomarkers such as IL-6 and presepsin." (PMID 40807041, 2025). "Additionally, IL-6 levels correlate with CT-verified bone erosion scores and kidney bacterial loads in the S. aureus septic arthritis model." (PMID 39204252, 2024). "In horses with naturally occurring and experimentally induced OA and septic arthritis, increased levels of inflammatory components, such as leukocytes, interleukin (IL)-1β, IL-6, tumor necrosis factor α (TNF-α), and matrix metalloproteinases, has been demonstrated." (PMID 36937015, 2023). "Surprisingly, in our study, a positive correlation of IL-6 level with the severity of bone destruction verified by μCT suggests that IL-6 may be a potential biomarker of the extent of bone damage in septic arthritis." (PMID 28152087, 2017). "Interestingly, serum levels of IL-6 were significantly correlated with the severity of bone destruction in septic arthritis." (PMID 28152087, 2017). "The findings of our study demonstrated that, although routinely used biomarkers such as serum CRP and synovial WBC remain valuable in diagnosing septic arthritis, incorporating novel biomarkers, such as PTX3, IL-6, and presepsin, could enhance diagnostic accuracy." (PMID 40807041, 2025). "IL-6 may be used as a biomarker for bone destruction in septic arthritis." (PMID 28152087, 2017). "Importantly, IL-6 positively correlated to the severity of bone destruction verified by μCT, suggesting that IL-6 may be used as a biomarker for joint damage in septic arthritis." (PMID 28152087, 2017).
septic arthritis (continued). "This suggests that IL-6 may be used as a biomarker for bone erosion in septic arthritis." (PMID 28152087, 2017). "During septic arthritis pathogenesis, macrophages secrete transforming growth factor-beta (TGF-β), IL-6, TNF-α, and IL-1β, cytokines with significant roles in NF-κB activation and osteoclast differentiation, perpetuating the inflammatory milieu and bone resorption." (PMID 40005560, 2025). "Mice infected with S. aureus lacking PSMα had better weight development and lower bacterial burden in the kidneys compared to mice infected with the parental strain, whereas mice infected with bacteria lacking PSMβ strain developed more severe septic arthritis accompanied with higher IL-6 and KC." (PMID 36065015, 2022).
Thromboembolism (17 papers, 2014 to 2025). The formation of a blood clot inside a blood vessel that subsequently travels through the blood stream from the site where it formed to another location in the body, generally leading to vascular occlusion at the distant site. "An association between IL-6 and increased risk of vascular thrombosis and thromboembolism is supported by experimental results and observational studies." (PMID 32629875, 2020). "However, SARS CoV-2 infection may predispose to thromboembolism 34, in which elevated levels of proinflammatory factors (including IL-6, GM-CSF, IL1B, and IFN-γ) may play a role 35-38." (PMID 33613111, 2021). "It is easy to implement into everyday clinical practice, as it includes four important parameters (age, IL-6, D-dimer, and serum albumin), reflecting the main pathophysiological mechanisms of the disease (inflammation, thromboembolism and cytokine storm)." (PMID 37627912, 2023). "On the other hand, clinical biomarker candidates associated with hypercoagulation statuses such as serum TFPI2, thromboembolism, plasma D-dimer, and plasma IL6 should also be evaluated for changes over time." (PMID 35565252, 2022). "Increase of peripheral vWF and IL6 levels after procedure supports current AF ablation management with careful control of post-procedural anticoagulation to avoid ablation-related thromboembolism." (PMID 25390649, 2014). "Studies in cerebral venous thrombosis (CVT) have shown extensive crosstalk between inflammatory cytokines such as C-reactive protein, IL-6 (interleukin-6), etc. and coagulation factors, demonstrating that inflammation plays an important role in thromboembolic disease." (PMID 35309326, 2022). "Several studies have reported that PM exposure enhances interleukin-6 (IL-6) and tumor necrotic factor-α (TNF-α) activation, contributing to the inflammatory process and resulting in thromboembolism." (PMID 39091522, 2024).